BRCA1 (BRCA1 DNA repair associated)
Diseases named in the same sentence as BRCA1 in open-access papers (continued):
Sharing a sentence is not in itself a finding about the gene and the disease.
tumor (continued). "For example, genes that are more relied upon by tumor cells as a result of the loss of BRCA1 function can be targeted for inhibition and result in cell death." (PMID 22032724, 2011). "This has resulted in a BRCA1-like classifier based on specific aberrations of BRCA1-mutated breast cancers compared to sporadic tumours." (PMID 22032731, 2011). "This is a reasonable assumption since more than 90% of mutation carriers in our sample were recruited prior to 2007, when it was uncommon to use tumour pathology in selecting individuals for BRCA1 and BRCA2 mutation screening." (PMID 22053997, 2011). "The BRCA1-likeaCGH group consisted of germline BRCA1-mutated cases and sporadic tumours with low BRCA1 gene expression and/or BRCA1 promoter methylation." (PMID 22032731, 2011). "We sought to further investigate the value of using family history and tumour morphologic features in selecting women for BRCA1 mutation testing." (PMID 21281505, 2011). "It is well accepted that BRCA1 deficiency leads to the dysregulation of DNA repair pathways, which in turn renders tumour cells more vulnerable to DNA damaging agents such as platinum-based chemotherapy." (PMID 22312502, 2011). "By combining training, test set and the prospective validation set, we had 40 tumours from patients known to be BRCA1 mutation carriers." (PMID 22032731, 2011). "Of the 58 probands whose tumours had both high mitotic index and trabecular growth pattern, 21 (36%) were BRCA1 mutation carriers." (PMID 21343941, 2011). "Loss of BRCA1 expression is a marker of tumour aggressiveness and correlates with CD44+ tumour cell phenotype." (PMID 23508738, 2011). "A total of 29 (6%) of the 452 probands whose tumours had undergone pathology review were found to be BRCA1 mutation carriers." (PMID 21343941, 2011). "In summary, recent evidence suggests that loss of BRCA1 function impairs normal breast differentiation thereby facilitating tumour initiation." (PMID 21609478, 2011). "This study emphasises the value of combining information about family history, age at diagnosis and tumour morphology when selecting women for germline BRCA1 mutation testing as well as including a screen for large genomic alterations." (PMID 21281505, 2011). "BRCA1-associated tumours are more often estrogen receptor (ER), progesterone receptor (PR), and human epidermal growth factor 2 (HER2) negative compared to their sporadic counterparts." (PMID 22312502, 2011). "Tumours with DNA repair defects, such as those arising from patients with BRCA1/2 mutations, are more sensitive to PARP inhibition." (PMID 20877358, 2010). "This basal tumour subtype exhibits a poorer prognosis than other subgroups, occurs with high frequency in BRCA1-mutated tumours and occurs more frequently in younger women." (PMID 20678196, 2010). "Despite the genetic disparity, the similarities in behaviour between these sporadic tumours and BRCA1 and BRCA2 deficient tumours has been termed ‘BRCAness’." (PMID 24281034, 2010). "From this study, it was inferred that tumours with BRCA1 mutations are highly sensitive to anthracycline-based chemotherapy regimens." (PMID 20219108, 2010). "Beclin 1 was mapped to a tumor susceptibility locus approximately 150 kb centromeric to BRCA1 on human chromosome 17q21." (PMID 20230646, 2010). "Many of these genes identified by loss of heterozygosity and allele-specific expression are known or putative tumor suppressor genes, such as BRCA1, MSH3 and SETX, which participate in DNA repair pathways." (PMID 21108794, 2010).
tumor (continued). "Although a target gene in this region is still to be identified, several candidates do exist (for example, PIK3R1 located on chromosome 5q13.1, previously found to be homozygously deleted in a BRCA1-mutated tumor)." (PMID 20576095, 2010). "The tumors clustered in two branches: 6 luminal tumors and 47 of the 48 BLBCs/BRCA1-mutated tumors clustered in one branch, whereas 1 BRCA1-mutated tumor and 42 of the 48 luminal-H/J tumors clustered in the other branch." (PMID 21118481, 2010). "For example several promising clinical trials are based on the use of inhibitors of the DNA damage-responsive enzyme PARP1 as a means to selectively target BRCA1-deficient tumor cells." (PMID 21103343, 2010). "The molecular pathway involved in DNA repair, particularly the role of BRCA1/2 proteins, would suggest a profile of tumor resistance to ionizing radiation (IR) in case of BRCA1/2 mutation, due to underlying in vitro effects." (PMID 20074364, 2010). "As expected, individuals with ER-negative tumours, or with ER-negative tumours diagnosed in their family members, are predicted to have a higher BRCA1 mutation carrier probability." (PMID 20482762, 2010). "The BRCA1-mutated tumor group had significantly more CNAs compared with the sporadic control tumor group between thresholds of 0.08 - 0.24." (PMID 20735817, 2010). "We applied comparative-KC-SMART to the normalized aCGH data of the BRCA1-mutated tumor group and the BLBC group." (PMID 21118481, 2010). "In our example, the BRCA1 mutation carrier probability is increased over fourfold when the mother's tumour is ER-CK14+CK5/6+ as compared with when it is ER-negative, but information on basal CK is unavailable." (PMID 20482762, 2010). "Recently, inhibitors of the DNA repair proteins, poly(ADP-ribose) polymerase 1 and 2 (PARP1/2), have been shown to be selectively cytotoxic to tumour cells with BRCA1 or BRCA2 deficiency." (PMID 20877358, 2010). "If both basal markers CK5/6 and CK14 are expressed on a TN tumour, the probability of carrying a BRCA1 mutation is 0.64." (PMID 20482762, 2010). "Tumours from germline BRCA2 mutation carriers had a higher degree of CpG methylation as compared with BRCA1-mutated, other familial and sporadic tumours (P = 0.007, ANOVA)." (PMID 20565864, 2010). "We compared gains and losses specific for the BLBC/BRCA1-mutated tumor groups relative to the luminal tumor groups." (PMID 21118481, 2010). "BRCA1 deficiency is believed to result in deregulation of the carefully coordinated DNA repair cascade and thereby renders tumor cells more vulnerable to DNA damaging agents and genomic instability." (PMID 20182637, 2010). "When evaluated with three-dimensional volume reduction using 50% of the PR/SD border, Spearman's analysis showed that the presence of BRCA1-positive baseline foci associated with poor EC tumor response (P = 0.0067)." (PMID 20205718, 2010). "It is worth noting that all of the ESR1-negative BRCA1 tumours in group A, which show low expression of NFκB, harboured truncating mutations in the central portion of BRCA1 that are thought to trigger the nonsense-mediated mRNA decay mechanism." (PMID 19826428, 2009). "All of the ESR1-negative BRCA1 tumours with low expression of NFκB originated from BRCA1 truncating mutations that probably led to a complete absence of the protein through the nonsense-mediated mRNA decay mechanism (NMD)." (PMID 19826428, 2009). "One of the GII-high subgroups (n = 11) was enriched with tumours displaying BRCA1 abnormalities (6 of 11) defined as an instance of a BRCA1 germline mutation or epigenetic silencing of the BRCA1 gene (Fisher's exact test, P = 0.006)." (PMID 19589159, 2009). "Nevertheless, DZNep shows remarkable selectivity in inhibiting BRCA1-deficient tumor cells compared with BRCA1-proficient tumor cells." (PMID 19709408, 2009). "Tumours derived from BRCA1 germline mutation carriers have previously been shown to predominantly display basal-like phenotypes." (PMID 19589159, 2009).
tumor (continued). "The BRCA1-deficient tumours arising in this model showed a prolonged response to the clinical PARP inhibitor olaparib without signs of toxicity." (PMID 19904273, 2009). "BRCA1-associated tumours, the vast majority of which are ER-negative, are also effectively prevented by removal of the ovaries." (PMID 19491898, 2009). "Tumours derived from BRCA1 or BRCA2 germline mutation carriers have generally lost the wild-type BRCA1 or BRCA2 alleles, respectively." (PMID 19589159, 2009). "We aimed to characterise aromatase transcriptional regulation in non-tumour containing breast adipose and ovary of women with pathogenic BRCA1 mutations, who had undergone prophylactic or therapeutic mastectomy or prophylactic oophorectomy." (PMID 19445691, 2009). "All tumours within this subgroup analysed for loss of heterozygosity at the BRCA1 locus displayed allelic imbalance (Fisher's exact test, P = 0.003)." (PMID 19589159, 2009). "They found that 6 of 24 (25%) patients with an ER-negative, high-grade tumour had a germline BRCA1 mutation." (PMID 19298662, 2009). "The genomic regions on chromosomes 4, 5 and 10 reported here to characterise the BRCA1-related subgroup overlap with those previously reported to distinguish tumours derived from BRCA1 germline mutation carriers." (PMID 19589159, 2009). "For example, the tumor microenvironment causes hypoxia, which represses the E-Cadherin, BRCA1, and MLH1 tumor suppressor genes." (PMID 19279688, 2009). "We found that increasing or decreasing our estimates of tumor sizes at clinical presentation in BRCA1 mutation carriers or in normal-risk women over a 2-fold range had a negligible effect on our conclusions." (PMID 19636370, 2009). "BRCA1 tumours with HIF-1α expression was associated with a shorter relapse-free (P=0.049) but not overall survival (P=0.764)." (PMID 19724277, 2009). "As a result of this large deletion, secondary mutations in Brca1 cannot restore Brca1 function and serve as a mechanism for platinum resistance in the mouse tumours." (PMID 19904273, 2009). "More recently, it has been suggested that most tumours arising in BRCA1 mutation carriers display a basal-like phenotype, with the percentages reported ranging from 44 to almost 100%." (PMID 19826428, 2009). "For example, pathway activities associated with basal subtype tumours involve Ephrin receptor, BRCA1 and integrins." (PMID 20003408, 2009). "Because familial BRCA1 tumours resemble basal-like tumours in terms of their phenotype it is of interest to note here that the genomic alterations that characterise the BRCA1-related subgroup overlap with those associated with basal-like tumours." (PMID 19589159, 2009). "Generally, about half of the patients with BRCA1 gene mutations present the phenotype ER(-)/HER2(-)/EGFR(+) of the basal type of tumor, which is usually associated with poor prognosis." (PMID 18405391, 2008). "Previous studies found significant discrepancies between human disease and some mouse Brca1 deficient tumor models." (PMID 18394172, 2008). "Patients with BRCA1-linked hereditary tumours have a favourable survival compared to sporadic tumours, possibly because of a good response to chemotherapy." (PMID 18628764, 2008). "In the study conducted Lakhani and coworkers, 57.6% of the BRCA1-associated tumours stained positive for CK-5/6 and 60.6% for CK-14." (PMID 18275599, 2008).
tumor (continued). "It must also be taken into consideration that while most tumours arising in BRCA1 mutation carriers have typical pathology, a sizeable minority do not." (PMID 18269736, 2008). "Other authors have claimed that BRCA1 methylated tumours have distinct pathologies to those seen in BRCA1 mutated tumours." (PMID 18269736, 2008). "The general features of basal phenotype tumours are the same as those of tumours in BRCA1 mutation carriers." (PMID 18275599, 2008). "We also detected CK-14-positive staining among 27% of BRCA2 associated tumours and 21% of the non-BRCA1/BRCA2 associated tumours." (PMID 18275599, 2008). "Alterations in the pattern and efficiency of alternative splicing of several pre-mRNAs (e.g. CD44, BRCA1, WT-1) have been implicated in tumourigenesis and correlated with tumour progression." (PMID 18949081, 2008). "In univariate analysis, CK-14 was significantly associated with tumours from BRCA1 (39%; P < 0.0005), BRCA2 (27%; P = 0.011), and non-BRCA1/BRCA2 (21%; P < 0.005) families, as compared with sporadic tumours (10%)." (PMID 18275599, 2008). "Possibly, ineffective DNA repair in BRCA1-linked tumours results in specific mutations of the PTEN gene." (PMID 18628764, 2008). "We further evaluated 35 high grade serous/undifferentiated tumours that we divided into four groups based on BRCA1 mutation status, expression, and promoter hypermethylation." (PMID 18208621, 2008). "We found that those tumours with BRCA1 loss through genetic events differed according to several parameters from tumours with loss of BRCA1 due to epigenetic events." (PMID 18208621, 2008). "Although transplantation preserves gene expression profile of the original Brca1 deficient tumor, it offers only a limited potential for tumor expansion for further studies since the starting material is a single mouse tumor." (PMID 18394172, 2008). "Tumours from two carriers of the G1738R variant differed from each other in most respects, with only one displaying features characteristic of BRCA1 tumours." (PMID 18036263, 2007). "We have observed that two of the three tumours from carriers of functionally abrogated BRCA1 alleles display BRCA1-like features." (PMID 18036263, 2007). "For example, in some TgMMTV-Wnt1, DMBA-induced, and Brca1-deficient strain tumors, distinct regions of single positive K5 and K8/18 cells were observed within the same tumor." (PMID 17493263, 2007). "Building on our previous studies, we selected four UVs for additional analyses, including tumour immunohistochemistry using markers known to be associated with BRCA1 mutation status, and in vitro assays to examine the effects on BRCA1 function." (PMID 18036263, 2007). "We also found a substantial proportion of the BRCA1 methylated tumours to be of grade 3 and an indication for an association between BRCA1 methylation and early age of onset." (PMID 16846527, 2006). "A deficiency of Chk2 partially rescued the defective development and growth of BRCA1 deficient T-cells but enhanced tumour development." (PMID 16563154, 2006). "Hypermethylation of PTEN was also associated with low-grade tumor, whereas, BRCA1 was associated with high-grade tumor (P = 0.026, 0.033 respectively)." (PMID 16928264, 2006).
tumor (continued). "The BRCA1 methylated tumours were significantly associated with estrogen receptor (ER) negativity (P = 0.0475) and displayed a trend for BRCA1 AI (P = 0.0731) as well as young-age at diagnosis (≤ 55; P = 0.0898)." (PMID 16846527, 2006). "Recently, cDNA expression analyses have suggested a basal epithelial phenotype for BRCA1 tumors and expression of cytokeratins 5/6 have been associated with BRCA1 tumours." (PMID 15987451, 2005). "Correlating LOH of the BRCA-1 locus to morphology in a study of sporadic tumours also showed an association with extremely high mitotic counts – occasionally exceeding 100 per 10 high power fields." (PMID 15700031, 2005). "It is noteworthy here that, although ER negativity has been considered a hallmark of BRCA1 tumours, logistic regression analysis indicated that this was not an independent marker but was dependent on the age of diagnosis and tumour grade." (PMID 15642173, 2005). "A large majority (20 of 22 tumours) of BRCA1-associated tumours were also ER-negative and erbB2-negative in our study, in accordance with the high frequency of ER-negative tumours among BRCA1 carriers." (PMID 15642173, 2005). "Recently, cDNA expression analyses have suggested a basal epithelial phenotype for BRCA1 tumours and expression of cytokeratins 5/6 has been associated with BRCA1 tumours." (PMID 15642173, 2005). "We performed the analysis of BRCA1 and BRCA2 genes in 14 women with this histological tumor subtype and found three truncating mutations (21.4%) in exon 11 of the BRCA1 gene." (PMID 16168118, 2005). "The prevalence of occult tumours found in their series at prophylactic surgery in 27 BRCA1 mutation carriers is 18.5%." (PMID 15083174, 2004). "In our series, five occult tumours were found in 58 BRCA1 germline mutation carriers (8.6%), who had undergone prophylactic salpingo-oophorectomy." (PMID 15083174, 2004). "In both patients, the presence of a BRCA1 mutation was confirmed and a loss of the wild-type BRCA1 allele in both tumours was shown." (PMID 15083174, 2004). "This would suggest that the increase in cell proliferation with associated genetic mutations common to all tumours should cause an increase in BRCA1 transcription and translation." (PMID 12698194, 2003). "Opposed to this is the association of GMP with BRCA1 mutations and higher nuclear grade, both of which appear to increase tumour responsiveness to chemotherapy." (PMID 12966421, 2003). "It has been shown that BRCA1 mRNA expression levels are the lowest in tumours of mutation carriers, intermediate in tumours of sporadic cancers, and highest in the surrounding normal tissues from either mutation carriers or sporadic cancers." (PMID 14583770, 2003). "Alterations in the pattern and efficiency of alternative splicing of several pre-mRNAs (e.g. CD44, BRCA1, WT-1) have been implicated in tumorigenesis and correlate with tumour progression." (PMID 12087473, 2002). "Tumours from patients with BRCA1 germline mutations (n= 10) were compared to an age-matched sample of other patients (n= 50) from the same cohort." (PMID 11720473, 2001). "Given that PD-1 blockade can restore T cell function and reduce tumor-intrinsic AKT signaling 25, the observed decrease in pAKT likely reflects a dual effect of enhanced antitumor immunity and suppression of tumor cell survival signaling in BRCA1-deficient tumors." (PMID 41208884, 2025). "We also examined whether the low HRD scores obtained in BRCA2- and BRCA1-mutated cases in our study are attributed to suboptimal tumor cell content in the corresponding tissue samples." (PMID 41465280, 2025).